ARG1 (arginase 1)
Diseases named in the same sentence as ARG1 in open-access papers (continued):
Sharing a sentence is not in itself a finding about the gene and the disease.
tumor (continued). "Compared with WT controls, the protein expression of MHC I, MHC II, TNF-α and IFN-γ were higher, while the expression of Arg-1 and iNOS were lower in Lnk–/– tumor MDSCs." (PMID 40796725, 2025). "Tumor-educated neutrophils and monocytes acquire immunosuppressive functions, including arginase-1 expression and anti-inflammatory cytokine production." (PMID 40358184, 2025). "Tmem119+ cells (microglia) were consistently found at the invasive tumor edge and in the surrounding brain tissue, and displayed low or undetectable levels of Arg1." (PMID 40281508, 2025). "Mechanistically, TGF-β signaling via Smad2/3 phosphorylation suppresses pro-inflammatory pathways while upregulating arginase-1 and MMPs, facilitating tumor angiogenesis and extracellular matrix degradation, thereby promoting metastasis." (PMID 40387965, 2025). "Analysis of CH25H and ARG1 IF staining on these serial sections revealed a significant increase in the infiltration of MDSCs within CRC tumor tissues as tumor progression advanced." (PMID 41020041, 2025). "Regarding immune cell populations in Hi-Myc Pb-RON mice, prostate and subcutaneous tumors showed increased F4/80+ cells, Arginase-1 expression, and tumor cell CCL2 secretion compared to Hi-Myc controls." (PMID 40282397, 2025). "In TNBC, M2-polarized tumor-associated macrophages (TAMs; CD163+) suppress effector T-cell function via ARG1, while exosomal LAP-TGF-β1 contributes to immunosuppression by reshaping the metastatic niche." (PMID 41573551, 2025). "Clostridium difficile activates the YAP/TAZ signaling pathway, inducing TAMs to express VEGF and arginase-1 (Arg1), thereby promoting tumor angiogenesis and immune evasion." (PMID 41450920, 2025). "Blocking the interactions between Apo-A1 and its receptors reduced arginase-1 expression in neutrophils treated with tumor tissue culture supernatant (TTCS)." (PMID 40358184, 2025). "Analysis of tumor-infiltrating lymphocytes also demonstrated that monocytes, macrophages, and ARG1+ macrophages were decreased and CD8+ T cells were increased with treatment of K63-pe." (PMID 39883522, 2025). "We also analyzed the expression of M1 markers (IL‐1β, Nos2, TNFα) and M2 markers (Arg‐1, CD206, IL‐10) in tumor‐associated macrophages." (PMID 39791593, 2025). "Consistent with in vivo data, targeting ISCU also reduced CD206 and Arg1 protein expressions in tumor, as well as the presence of CD206+ macrophage infiltrations in TMEs." (PMID 40541964, 2025). "The tumor inhibitory effect of adiponectin is related to ARG1, it can inhibit the down-regulation of ARG1 in inflammatory tissues, thereby restoring T cell viability." (PMID 41200178, 2025). "In conclusion, Arg metabolic reprogramming plays a dual regulatory role on TAMs through iNOS and ARG pathways, but in immunosuppressive TME of biliary and pancreatic malignancies, ARG1-dominated tumor-promoting effects are dominant." (PMID 41281760, 2025). "Similar to M2-like macrophages, ARG1-expressing TAMs and TANs deprive T cells from arginine thereby suppressing their anti-tumor effects." (PMID 39863828, 2025). "They mediate immunosuppression primarily through M2 polarization (characterized by a CD206+/arginase-1 (Arg-1)+ phenotype), thereby protecting tumor cells from CD8+ T-cell-mediated cytotoxicity." (PMID 40817844, 2025). "Both human and mouse glioblastomas (GBMs) demonstrate elevated expression of ARG1 and ARG2 in tumor cells and infiltrating macrophages and microglia, causing a depletion of L-arginine, which is essential for activating T cells and natural killer (NK) cells." (PMID 40427130, 2025). "Aside from tumor cell consumption, TAMs and MDSCs exacerbate arginine depletion via overexpression of arginase 1 (ARG1)." (PMID 41488637, 2025). "Arginase 1 (ARG1) is a key enzyme that catalyses the hydrolysis of L-arginine, which is primarily released by tumour-associated myeloid cells in the tumour microenvironment." (PMID 40234383, 2025).
tumor (continued). "Conventionally, M2-polarized TAMs facilitate tumor immune evasion through IL-10/TGFB1 secretion or ARG1 overexpression." (PMID 40959090, 2025). "Flow cytometry analyses further strengthened these observations, spotlighting a reduction in the tumour-favouring Mertk+ and Arg1 + M2 macrophages, while showing an increase in the iNos+ M1 phenotype." (PMID 40287432, 2025). "Our findings indicate that CH25H and its metabolite, 25HC, which are elevated in tumor‐infiltrating MDSCs, upregulate the expression of ARG1 and enhance immunosuppressive activity by inhibiting the STING–TBK1–RIPK3 signaling axis." (PMID 41020041, 2025). "Tumor-infiltrating dendritic cells (TIDCs) decrease the expression of CD3ζ in T cells through the action of ARG1, inducing anergy in CD8+ T cells and thereby promoting tumor progression." (PMID 39905317, 2025). "Following the in vitro experiments, neutrophils treated with primary biopsy tumor tissue supernatants exhibited increased arginase-1 expression." (PMID 40358184, 2025). "In murine tumor models, high ARG1 expression is typically observed in monocyte-derived cells, whereas in humans, such high expression is most prevalent in polymorphonuclear cells rather than monocytes." (PMID 41488637, 2025). "By contrast, systemic NOD1 activation can expand MDSCs and sustain Arg1-dependent suppression, fostering tumor-permissive microenvironments in CRC models." (PMID 41339918, 2025). "We believe that certain components of the tumor proteasome pool can be involved in the regulation of Chil3 and Arg1 expression." (PMID 40918453, 2025). "ARG1 functions as a metabolic checkpoint in immune cells by depleting arginine, creating an immunosuppressive environment that facilitates tumor immune evasion." (PMID 41155404, 2025). "Arginase-1 (ARG1) is expressed in the cytoplasm of hepatocytes and is involved in anti-inflammatory, tumor immune, and immunosuppressive functions." (PMID 41293169, 2025). "Arginase-1 activity has long been recognized as an important immunoregulatory mechanism, particularly in M2 macrophages and MDSCs within the tumor context." (PMID 41208994, 2025). "The mRNA expression of tumor-supportive macrophage genes, such as Arg-1, was reduced by shTRIM32-CM, whereas the expression of cytotoxic response genes IL-1β, IL-12 A, and CD86 was elevated by shTRIM32 cell supernatants." (PMID 41163195, 2025). "The results showed that NOS and Arg-1 activity in Lnk–/– tumor PMN-MDSCs were decreased, while the expression of IFN-γ and TNF-α was increased." (PMID 40796725, 2025). "Granulocyte–macrophage colony-stimulating factor (GM-CSF) produced by tumor cells and lactic acid synergistically induce ARG1 expression in TAMs." (PMID 39863828, 2025). "Therapeutic strategies that target these immunosuppressive pathways, such as ARG1 inhibitors or PD-L1 blockers, are currently under investigation and offer potential for restoring effective anti-tumor immunity." (PMID 40227814, 2025). "Targeting TAMs’ metabolic nodes, such as inhibiting ARG1 or blocking fatty acid uptake, can restore their anti-tumor function and inhibit liver metastasis." (PMID 41164182, 2025). "Our present study highlights a pro-tumor role of neutrophils in UTUC through arginase-1 upregulation, contributing to T cell suppression." (PMID 40358184, 2025). "Arg1 in particular is interesting because TDE-associated Arg1 was found to deplete the TME of arginine, which starved T cells and inhibited their anti-tumor effector functions." (PMID 39796781, 2025). "An ARG1 inhibitor is already being tested in several clinical cancer studies as inhibition of ARG1 is suggested to reactivate tumor immunity." (PMID 40474277, 2025). "GBM tumors exploit this pathway by overexpressing enzymes such as IDO1 and arginase-1, allowing the tumor cells to rapidly consume tryptophan and arginine." (PMID 40507361, 2025).
tumor (continued). "Correlation analysis showed that IHC score of DTX2 was positively correlated with the number of ARG1+ CD66B+ cells in tumor tissues." (PMID 39733452, 2025). "A negative correlation was observed between the proportion of infiltrating CD4+ T cells and arginase-1 expression in tumor-infiltrating neutrophils." (PMID 40358184, 2025). "The qPCR analysis of total mRNA from tumor tissues revealed significant upregulation of M1 markers Nos2, Il1b, and Il6, along with marked downregulation of M2 markers Mcr1, Arg1, and Il10." (PMID 39908200, 2025). "These macrophages secrete CCL2, VEGF, and arginase-1, which recruit additional suppressive myeloid cells and deplete nutrients essential for T-cell activation, thereby fostering immune escape and tumor progression in NSCLC." (PMID 41584608, 2025). "We observed IKE treatment markedly upregulated TNF-α level and downregulated Arg-1 level in WT and Lnk-/- tumor MDSCs." (PMID 40796725, 2025). "Previous studies have established the NOS2/ARG1 axis as a critical modulator of tumor progression and metastasis." (PMID 41573553, 2025). "This process ultimately results in the upregulation of ARG1 levels, enhancing the immunosuppressive capacity of MDSCs and facilitating tumor immune escape." (PMID 41020041, 2025). "This interaction promotes Arg1 and iNOS expression in MDSCs, further increasing their immunosuppressive activity and contributing to tumor progression." (PMID 40452814, 2025). "In contrast, M2 macrophages are induced by IL-4 and IL-13, which activate STAT6 signaling, promoting the expression of arginase 1 (Arg1) and facilitating tissue repair, angiogenesis, and immune suppression, as well as exhibiting tumor-promoting properties." (PMID 41002423, 2025). "MDSCs secrete immunosuppressive factors such as arginase-1 and reactive oxygen species (ROS), which impair T cell function and enhance tumor survival." (PMID 39949765, 2025). "Immunostaining of the tumor showed hepatocyte, arginase 1, Melan-A, HMB-45, CK20, PAX8, CD10, CA9, and TFE3 negativity, as well as AE1/AE3 and CK7 positivity, leading to the diagnosis of clear cell carcinoma of the liver." (PMID 41018392, 2025). "Spatial analysis of tumors from colorectal cancer patients reveals that ARG1 expression in neutrophile granulocyte increases with proximity to the tumor." (PMID 41488637, 2025). "To analyze the neutrophil properties, we used the following frequently mentioned profiles: pro-tumor anti-inflammatory profile (Mmp9, Vegfa, Arg1, Nos2, Ccl17, Il10) and anti-tumor pro-inflammatory profile (Icam1, Tnfa)." (PMID 40001601, 2025). "Mechanistically, cyclooxygenase 1 and 2 (COX-1 and −2)–dependent PGE2 production by tumor cells promotes ARG1 expression in MDSCs in a paracrine fashion." (PMID 39863828, 2025). "ARG1 is an enzyme that depletes L-arginine, thereby suppressing T-cell function and promoting immune evasion, which facilitates tumor growth and progression." (PMID 40665092, 2025). "Lactate produced by cancer cells stabilizes extracellular signal-regulated kinases 1/2 (ERK1/2), signal transducer and activator of transcription (STAT) 3, and HIF-1α to induce ARG-1, thereby inhibiting the T-cell function and promoting tumor growth." (PMID 39925801, 2025). "For example, in a mouse model of epithelial ovarian cancer, extracellular vesicles containing Arg1 are transported into lymph nodes and taken up by DCs, thereby inhibiting the proliferation of T cells and further leading to tumor growth and immune evasion." (PMID 40131539, 2025). "Doxorubicin chemotherapy reduced MDSC frequency, Arg1, iNOS and ROS expression, and enhanced anti-tumour T cell tumour infiltration." (PMID 38464388, 2024).
tumor (continued). "Despite a significant value dispersion, the results of real-time PCR assays revealed that the expression of Arg1 mRNA in peritoneal macrophages of mice of both groups was significantly higher than in tumor-bearing mice." (PMID 38455363, 2024). "Hydrogels loaded with norvaline and doxorubicin hydrochloride achieved high drug loading and controlled release of norvaline to block the ARG1 pathway, showing promising efficacy in primary tumor ablation and inhibition of tumor metastasis." (PMID 39735340, 2024). "Arg1 protects against inflammation, tumor immunity, fibrosis, and immunosuppression-related diseases mainly via its regulatory effects on L-arginine metabolism in immune cells, including macrophages." (PMID 39456653, 2024). "Blocking MyD88 with the novel inhibitor TJ-M2010-5 suppressed MDSC Arg1 and iNOS expression enhancing anti-tumour immunity." (PMID 38464388, 2024). "Accordingly, decreased CD3ζ expression is found in the peripheral or tumor-infiltrating T cells of cancer patients with high myeloid ARG1 expression." (PMID 39211039, 2024). "Macrophages are activated by tumor-derived lactate signaling through hypoxia-inducible factor 1α (HIF1α), leading to a tumor-promoting state that is marked by increased production of arginase 1 (Arg 1) and VEGF." (PMID 38983918, 2024). "Tumor-associated microglia in GB are pro-tumor M2-like, as evidenced by the overexpression of markers such as CD206 and ARG1." (PMID 38523646, 2024). "M2 macrophages express a high level of arginase 1 (Arg1) to generate L-ornithine and urea, which are precursors of polyamine and proline synthesis contributing to tumor proliferation and progression." (PMID 38632627, 2024). "TAMs, through their production of arginase-1, also metabolize arginine to ornithine and putrescine, which can promote tumor cell proliferation, while also suppressing cytotoxic T cells and downregulating the tumor-cytotoxin nitric oxide (NO)." (PMID 39410029, 2024). "Arginase 1 (ARG1) is released in response to G-CSF and TGFβ in the microenvironment and is also used as a marker for pro-tumor N2 neutrophils." (PMID 39061147, 2024). "First, lactic acid from cancer cells can stimulate the expression of VEGF and ARG1 and promote the polarization of TAMs to the M2 phenotype through histone lactoacylation, leading to tumor cell proliferation." (PMID 39192979, 2024). "In patients with various cancer types, high ARG1 expression and activity is found in both circulating and tumor-infiltrating myeloid cells, with G-MDSCs as its major source." (PMID 39211039, 2024). "M2 macrophages heavily depend on glutamine entry into the TCA cycle and primarily rely on fatty acid β-oxidation and TCA cycling, facilitating the conversion of L-arginine into polyamines and L-proline through arginase 1 (Arg1) to support tumor growth." (PMID 39430253, 2024). "These cells expressed the enzyme Arg1 display tumorigenic functions with increased metastatic potential and tumor cell proliferation." (PMID 38339136, 2024). "Both hepatocyte markers (eg, HepPar1, arginase-1, and α-fetoprotein) and cholangiocyte markers (eg, cytokeratin 19 and carcinoembryonic antigen) are expressed in the tumor cells of int-CA." (PMID 39101773, 2024). "The study found that high Arg-1 expression in tumor tissues correlated with favorable clinicopathological features and longer recurrence-free survival (RFS), while elevated plasma Arg-1 levels were linked to poor clinical outcomes." (PMID 39409917, 2024). "The expression of inducible nitric oxide synthase (iNOS) and Arg1 in MDSCs increases significantly, which can directly inhibit the anti-tumor functions of T cells." (PMID 39596288, 2024). "Taken together, HES1 expression increased only when a tumor promoting stimulus was applied, and ARG1 expression also increased under the same circumstances." (PMID 39702544, 2024).
tumor (continued). "Tumor-derived lactate induced the M2-like polarization of TAMs through the induction of arginase 1 (Arg-1) expression via the hypoxia-inducible factor 1α (HIF1α) – VEGF pathway." (PMID 38842752, 2024). "Accordingly, other studies found tumour MDSCs to have superior immunosuppressive functions over MDSCs found in the periphery in line with the heightened Arg1 expression, and indeed tumour MDSCs strongly express the IL-4 and IL-13 receptors." (PMID 38464388, 2024). "Here, we revealed a significant decrease in the mRNA levels of the marker of M2 macrophages Arg1 in the tumor tissue in mice fed with grains enriched with anthocyanins but not in the group fed with control grain." (PMID 38891915, 2024). "The phosphorylation of STAT6 by ROP16 induces arginase-1 (Arg-1), which is involved in anti-inflammatory effects, tumor immunity, and immunosuppression-related diseases." (PMID 38297164, 2024). "The authors revealed that OvCa cells release Arg-1 in small extracellular vesicles (EVs), which mitigated anti-tumour immune responses by inhibiting T-cell activation and proliferation." (PMID 38592313, 2024). "Collectively, these data indicate that HCC tumor cells can be stratified into three distinct subtypes, characterized by the expression of ARG1, TOP2A, and S100A6, respectively." (PMID 39095854, 2024). "These exosomes promote the overexpression of PD-L1 in immature myelo-monocytic precursors and CD206+ macrophages, stimulating macrophages to produce arginase-1 and IL-10 to suppress anti-tumor immune responses and thereby accelerate tumor growth." (PMID 38779660, 2024). "The anti-tumor immunostimulatory effects of metformin were further emphasized by a decrease in the levels of PD-L1 and Arginase-1 as previously observed in breast and colon cancers." (PMID 37612575, 2024). "The ability of tumor secretions to induce ARG1 is completely lost in neutrophils isolated from mice with TLR2 or MyD88 knockouts." (PMID 38523155, 2024). "Conversely, the M2 type metabolizes arginine by arginase 1 (Arg1) and then by ornithine decarboxylase 1 to produce PAs for pro-tumor activities." (PMID 39191486, 2024). "We identified three subtypes in tumor cells, including ARG1+ metabolism subtype (Metab-subtype), TOP2A+ proliferation phenotype (Prol-phenotype), and S100A6+ pro-metastatic subtype (EMT-subtype)." (PMID 39095854, 2024). "Tumor-infiltrating M2 TAMs directly promote cancer growth and metastasis by secreting regulatory cytokines, including IL-10 and ARG-1, whereas M1 TAMs have the opposite effects." (PMID 39020380, 2024). "Neutrophils promoted tumor cell proliferation and metastatic processes by direct action on tumor cells or by secreting arginase 1, which inhibited the activation of T cells." (PMID 38686610, 2024). "ARG1 inhibitor treatment reduced tumor growth in Kras-driven NSCLC mice and increased both T-cell homing and activity." (PMID 39061147, 2024). "Nebulised anti-MDSC antibody RB6-8C5 treatment reduced mRNA levels of Arg1, leading to NK cell activation and enhanced tumour reduction." (PMID 38464388, 2024). "The proportion of Arg1-positive macrophages (%Arg1+ and F4-80+/ F4-80+) and Arg1-positive tumor cells (%Arg1 and CK8+/CK8+) were similar between tumors from WT and Ddr2−/− mice." (PMID 37996700, 2024). "The activation of the PI3K/Akt/mTOR signaling pathway in the tumor microenvironment upregulates Arg1 expression in TAMs." (PMID 38185636, 2024). "Tumor-derived lactate polarizes macrophages towards a pro-tumorigenic M2 cell fate that induces arginase-1 to deprive arginine in T and NK cells." (PMID 38216787, 2024). "Reduces proliferation of T and NK cells through expression of arginase-1 by tumor cells (degrades L-arginine needed for cell survival)." (PMID 38398094, 2024). "On the contrary, however, there are a lot of arginine metabolic enzymes in the tumor microenvironment (ARG Arginase-1, 1)." (PMID 39596288, 2024).